IL10 (interleukin 10)
Diseases named in the same sentence as IL10 in open-access papers (continued):
Sharing a sentence is not in itself a finding about the gene and the disease.
tumor (continued). "In addition, TNF-α activates the M2-type polarization of TAMs and secretes inhibitory factors such as IL-10 and TGF-β, further suppressing anti-tumor immune responses." (PMID 41376630, 2025). "For instance, IL-10-negative B cells exhibit elevated expression of Fas ligand (FasL) and mediate direct tumor cell killing through the Fas-FasL signaling pathway." (PMID 41285707, 2025). "Although LPA is a known mediator of cytokine release, its role in regulating IL-10 expression by tumor cells has not been described previously." (PMID 39187677, 2025). "By analysing IL1β, IL10, IL18, TNF-α, TLR4, GATA3, and CD68 expression in 50% of PCa HHV-infected FFPE with an elevated inflammation index (61.8%/21), we detected hyper-expressed levels of IL1β, IL18, and TNF-α in the tumour microenvironment." (PMID 40430084, 2025). "M2d macrophages secrete VEGF, IL-10, and CCL18, contributing to tumor progression by promoting angiogenesis and suppressing T cell proliferation, thereby facilitating immune evasion and tumor growth." (PMID 40055311, 2025). "Additionally, tumor-derived factors, such as VEGF, IL-6, and IL-10, can recruit MDSCs to the inflammatory TME, where they activate the STAT3 signaling pathway to produce more VEGF, establishing a positive feedback loop that promotes tumor angiogenesis." (PMID 40563367, 2025). "IL-10 suppresses the activation of T cells and DCs, whereas TGF-β promotes the differentiation of regulatory T cells (Tregs), which further dampen the anti-tumor immune response." (PMID 40486614, 2025). "Furthermore, our results demonstrated that the siRNA-mediated knockdown of DR6 abolished the effect of LPA on IL-10 expression and release, reinforcing the central role of DR6 in LPA-induced cytokine release by tumor cells." (PMID 39187677, 2025). "These tumor cells engage the SIRPα-CD47 axis to inhibit antigen-presenting cell phagocytosis, while glycolytic metabolites polarize TAMs toward M2 phenotypes, which secrete IL-10 to dampen immune responses." (PMID 40959090, 2025). "While immunosuppressive factors such as CCL2, CXCL12, IL-4, and IL-10 sustain an immune-excluded TME, pro-inflammatory mediators like IFN-γ, TNF-α, and CXCL10 counteract these effects by promoting immune cell infiltration and tumor suppression." (PMID 40330466, 2025). "M2-like TAMs can not only exacerbate immune escape by secreting immunosuppressive cytokines such as IL-10 and TGF-β, but also promote collagen synthesis by metabolically generating products such as PAs and proline that directly stimulate tumor cell proliferation and activate CAFs." (PMID 41281760, 2025). "Pro-tumor elements, such as regulatory T cells (Tregs) and MDSCs, create an immunosuppressive environment, inhibiting anti-tumor immunity via cytokines (TGF-β and IL-10) and immune checkpoint molecules (PD-L1, CTLA-4, TIM-3, TIGIT, and NRP1)." (PMID 40908470, 2025). "M2-polarized TAMs release IL-10 and TGF-β, which promote immune suppression and tumor development." (PMID 40309351, 2025). "Addressing these suppressive influences is crucial for effective anti-tumor immunity and can be exploited in ANXA1-high tumors, where PD-1 blockade or anti-IL-10 therapies might be effective." (PMID 40361334, 2025). "Therefore, experimental designs should integrate spatial and multi-omics pharmacodynamic indicators, such as the reduction of TAM-tumor-CAF neighbor clusters, decreased TREM2 or SPP1 TAM load, and normalization of CCL2, IL10, and TGFB." (PMID 41488638, 2025). "Upon their recruitment to tumors, newly activated macrophages are reprogrammed by tumor-derived factors, including TGF-β, IL-10, and hypoxic signals, into a phenotype that aligns more closely with tissue repair and immune suppression than robust tumor clearance." (PMID 40462895, 2025).
tumor (continued). "This new approach of IL-10-directed cancer therapy demonstrated low toxicity while exhibiting potent antitumor activity, primarily by reinvigorating and expanding terminally exhausted CD8+ tumor-infiltrating lymphocytes (TILs)." (PMID 40149345, 2025). "IL-10 can also be produced by non-immune cells, such as epithelial cells, keratinocytes, and some types of tumor cells, when certain conditions are met." (PMID 41156600, 2025). "Indeed, overexpression of miR155 induced repolarization of M2-activated macrophages into pro-inflammatory M1-like macrophages and also reduced tumor progression of esophageal cancer via downregulation of FGF2, IL-10, Arginase-1 and IL-22." (PMID 40050933, 2025). "Additionally, IL-10 plays a pivotal role in the JAK/STAT signaling pathway and can induce PD-L1 expression, facilitating immune evasion by tumor cells." (PMID 40881684, 2025). "These included TNFR and IL-10 phenotypes, which also expressed CD30; hence, targeting CD30+ Treg cells could substantially overcome Treg cell-mediated resistance to tumor growth." (PMID 40457060, 2025). "Tumor exosomes internalized by host cells upregulate phosphorylation of STAT3 and SMAD2/3 in recipient tissues, accompanied by partial excessive secretion of IL-10 and TGF-β1, thereby reshaping local and distant microenvironments to facilitate immune evasion." (PMID 41463331, 2025). "Finally, we co‐cultured CD4+ T cells with tumor cells for 48 h and found that the exogenous addition of CX3CL1 significantly promoted the secretion of IL10 and TGFβ." (PMID 39783838, 2025). "Tumor-derived factors such as VEGF, IL-10, and IDO can suppress DC function." (PMID 40825677, 2025). "Further confirmation by qPCR and flow cytometry showed that combining B.bif_K57 with the PD-1 inhibitor significantly increased the expression of immune-active cytokines, such as IFN-γ and IL-2, in the tumor, while reducing the expression of immune-suppressive cytokines like TNF-α and IL-10." (PMID 40469191, 2025). "Furthermore, in an LLC cell model, IL‐10 enhanced tumor cell resistance to apoptosis and activated the TLR4/IL‐10 cascade reaction, thus promoting tumor cell EMT." (PMID 39927632, 2025). "M2 macrophages can express IL10, IL-12, arginase 1, etc., and these promote Treg cell recruitment, epithelial-mesenchymal transition (EMT), extracellular matrix (ECM) remodeling, angiogenesis, and finally, tumor metastasis." (PMID 40297580, 2025). "Conversely, M2 macrophages, induced by IL-4, IL-13, IL-10, or TGF-β, play a pro-tumor role." (PMID 40908470, 2025). "Furthermore, IL-10 secreted by CD38+ B cells suppresses NK cell cytotoxicity 20, and IL-1β fosters tumor cell proliferation via immune-suppressive B cells." (PMID 40303346, 2025). "Additionally, IL-10/JAK1/STAT3 pathway activation induces vasculogenic mimicry, forming vasculogenic mimicry that support tumor blood supply." (PMID 41479912, 2025). "On the contrary, M2-TAMs create an immunosuppressive TME and favor tumor cells for invasion, metastasis, angiogenesis, and remodeling of the ECM by secreting high levels of anti-inflammatory cytokines such as interleukin IL-4, IL-13, and IL-10." (PMID 40805183, 2025). "On the one hand, many molecular pathways and cell functions are involved in regulating tumor immunity, and GBM cells produce effective immune inhibitory molecules, including transforming growth factor-beta (TGF-β), interleukin-10 (IL-10), and indoleamine 2,3-dioxygenase (IDO)." (PMID 40527884, 2025). "Moreover, El1405 intervention significantly increased the levels of TNF-α, INF-γ, and CD8 in the tumor microenvironment, while decreasing the levels of CD4, IL-6, IL-10, and TGF-β." (PMID 40568973, 2025). "In established tumors, NF-κB may also promote immunosuppression by increasing the levels of immunosuppressive cytokines (e.g., IL-10 and TGF-β) and recruiting myeloid-derived suppressor cells (MDSCs), thereby promoting tumor progression." (PMID 40562870, 2025).
tumor (continued). "However, tumor‐derived TGF‐β and IL‐10 impair DC maturation and function, reducing T‐cell activation." (PMID 41143064, 2025). "Within the tumor microenvironment, CAF- and MDSC-driven TGF-β/IL-10 secretion, hypoxia-induced ECM remodeling, and nutrient competition severely limit CAR-T-cell infiltration, persistence, and function, necessitating combination approaches to disrupt immunosuppressive networks and physical barriers." (PMID 41348261, 2025). "In TME, M2 TAMs secrete immunosuppressive factors such as IL-10 and vascular endothelial growth factor (VEGF), along with matrix metalloproteinases, which facilitate tumor progression and metastatic spread while simultaneously inhibiting the activation and proliferation of effector T-cells." (PMID 40281554, 2025). "IL-10 and TGF-β were also reduced in DCs from Cyp11a1cKO tumours." (PMID 40287432, 2025). "In NSCLC, increased IL-10 expression by TAMs correlates with more advanced stages of the disease, the presence of lymph node metastases, pleural invasion, lymphovascular spread, and lower differentiation of tumor cells, underscoring the significance of TAM-derived IL-10 in disease progression." (PMID 41179937, 2025). "Indeed, M2‐like TAMs contribute to a tumor‐promoting microenvironment by secreting anti‐inflammatory cytokines such as IL‐10 and TGF‐β, which can dampen the activity of TRM cells and hinder their ability to control tumor progression." (PMID 39802636, 2025). "Additionally, they secrete cytokines such as IL-10 and TGF-β, which have anti-inflammatory effects in normal and tumor tissues, respectively." (PMID 39354287, 2025). "Moreover, tumor cells release immunosuppressive factors such as TGF-β and IL-10, which further contribute to NK cell dysfunction." (PMID 40136652, 2025). "Tregs, characterized by the expression of Forkhead Box P3 (FOXP3), accumulate within the tumor bed and secrete immunosuppressive cytokines such as transforming growth factor beta (TGF-β) and interleukin-10 (IL-10), thereby inhibiting effective cytotoxic T lymphocyte (CTL) responses." (PMID 41179287, 2025). "Hence, this study chose to assess serum concentrations of TNF‐α, IL‐2, IL‐10, MMP‐9, and VEGF‐C to reflect the conditions of the tumor microenvironment before metastasis." (PMID 40808216, 2025). "In contrast, pro-tumor immune cells such as M2-type macrophages, regulatory T cells (Tregs), and MDSCs suppress immune responses by secreting inhibitory factors (e.g., TGF-β and IL-10) or depleting essential nutrients." (PMID 41425089, 2025). "In vivo, a significant reduction (~89%) in tumor burden and favorable modulation of inflammation, characterized by a decrease in pro‐inflammatory cytokines (TNF‐α, IFN‐γ, IL‐6, VEGF) and an increase in anti‐inflammatory IL‐10 was observed." (PMID 40908716, 2025). "Activation of the non-canonical NF-kB pathway can promote tumor cells to secrete immunosuppressive factors such as IL-10." (PMID 41488073, 2025). "Among the main cytokines involved in tumor immunity are IFN-γ, TGF-β, TNF-α, IL-10, and IL-17." (PMID 39860614, 2025). "Also of interest is the blockade of IL10, an anti-inflammatory cytokine whose high expression in TAMs in NSCLC correlates with tumor stage, size, lymph node metastasis, lymphovascular invasion, and differentiation grade." (PMID 39941714, 2025). "Similarly, expression of the microglia homeostatic genes P2RY12 and CX3CR1 declined with tumor grade, while expression of the immunosuppressive genes IL10 and F11R (JAM-A) increased with tumor grade." (PMID 38895459, 2025). "IL-10 has been demonstrated to impair CD8 T cell function across various tumor types, while TGF-β undermines T-cell immunity by promoting regulatory T-cell differentiation, further enhancing immunosuppression within the tumor microenvironment." (PMID 40236700, 2025).
tumor (continued). "Furthermore, tumor cells actively shape the immune microenvironment by secreting immunomodulatory cytokines such as CCL2, M-CSF, TNF, IL-10, and TGF-β, thereby amplifying the recruitment and M2 polarization of TAMs." (PMID 41459539, 2025). "The increase in IL-10 and VEGF levels in advanced ISS stages shows that as the disease becomes worse, there is more immune suppression and blood vessel growth happening in the tumor environment." (PMID 40647640, 2025). "Notably, M2 macrophages drive trastuzumab sensitivity by releasing immunosuppressive cytokines like interleukin-10 (IL-10) and transforming growth factor β (TGF-β) and metabolic reprogramming of tumor cells to create an immune-excluded phenotype." (PMID 40821778, 2025). "These macrophages secrete pro-tumour factors such as VEGF, IL-10 and TGF-β." (PMID 40495147, 2025). "These HMGB1-carrying TRAPs then directly educate B cells to become IL-10-producing immunosuppressive cells, which in turn suppress the activity of both CD4+ and CD8+ T cells, creating a potent barrier to anti-tumor immunity and fostering an environment conducive to therapy resistance." (PMID 41465435, 2025). "The immunosuppressive properties of TME are dominated by TAMs-M2-type TAMs inhibit the cytotoxicity of CD8+ T cells through the secretion of IL-10 and TGF-β, while enhancing the anti-apoptotic capacity of tumour cells, leading to a reduction in the killing efficiency of chemotherapeutic agents." (PMID 40495147, 2025). "Additionally, cytokines such as IL-6, IL-8, IL-10, TNF-α, and TGF-β demonstrate context-dependent activities, intricately regulating immune responses, tumor growth, and metastasis." (PMID 40909271, 2025). "Thus, TAMs can disturb anti-tumor immunity by suppressing T cells, NK cells, and NKT cells or by secreting anti-inflammatory cytokines of IL-10 and TGF-β." (PMID 40050933, 2025). "Furthermore, we assessed the level of secreted cytokines, including IFN-γ, TNF-a, IL-2, and IL-10, produced from the co-culture of CAR-T cells with tumor cells at an effector-to-target (E:T) ratio of 16:1." (PMID 40722671, 2025). "M2d macrophages, also referred to as tumor-associated macrophages, are driven by Toll-like receptor ligands, IL-6, and adenosine receptor activation, and contribute to angiogenesis and tumor progression by releasing TGF-β, IL-10, and vascular endothelial growth factor (VEGF)." (PMID 40722994, 2025). "In the AML microenvironment, IL-10 increases the proportion of Breg cells, promotes the secretion of immunosuppressive factors (including IL-10 itself and TGF-β), and suppresses effector T-cell function, thereby facilitating tumor immune escape." (PMID 40557150, 2025). "Cytokines such as Il-6 and TGF-β induce differentiation to Th17, which is associated with chronic inflammatory conditions, whereas anti-inflammatory cytokines IL-10 and TGF-β induce Tregs differentiation, which suppresses immune responses and aids in tumor evasion." (PMID 40429961, 2025). "Bcl-6+ hTregs produce IL-10 and TGF-β, and play a complex and dual roles in tumor immunity." (PMID 41041322, 2025). "Notably, many studies report a shift toward an M2-like phenotype, characterized by an increased expression of IL-10 and VEGF, along with decreased TNF-α levels—features indicative of immunosuppressive reprogramming and a tumor-permissive immune profile." (PMID 40940834, 2025). "The tumor microenvironment (TME) is a significant barrier, stimulating immunosuppressive variables such as MDSCs, M2-polarized macrophages, and cytokines, including IL-6, IL-10, and TGF-β, which restrict antitumor immunity." (PMID 40075634, 2025). "These cells release IL-10 and VEGF, and promote angiogenesis and tumor progression." (PMID 40109347, 2025). "Compounding this, platinum treatment may activate the STAT3 pathway by increasing IL-6, IL-10, and PGE2 production, leading to M2 polarization and tumor progression." (PMID 41280929, 2025).
tumor (continued). "IL-10 and IL-10RA immunostaining indicated that IL-10 was not expressed by tumors; however, IL-10RA expression was highly localized in tumor cells." (PMID 40666494, 2025). "Furthermore, hypoxia increases the mRNA and protein expression of anti-tumor immunity factors including TGF-β, IL-10, VEGF, CXCL12, PD-L1, FasL, and CD39 on CAFs." (PMID 40963621, 2025). "Conversely, M2-type macrophages secrete anti-inflammatory factors (IL-10, TGF-β, VEGF, etc.), which mainly mediate anti-inflammatory responses and Th2-type immune responses, thus participating in angiogenesis, EMT, immunosuppression, and tumor metastasis." (PMID 39975599, 2025). "In contrast, the expression levels of the M2-activtion markers CD206, TGFβ and IL-10 were significantly enhanced by co-culturing the tumor cells with non-activated U937 cells, relative to their single culture controls." (PMID 41462963, 2025). "NKG2D CAR-T cells specifically recognized NKG2DL-positive ESCC cells and secreted high levels of TNF-α, IFN-γ, IL-10, and IL-2 in overnight cocultures, while no response was observed in the absence of target tumor cells." (PMID 40510363, 2025). "Some studies suggest that this negative regulation could be attributed to the up-regulation of IL-10, TGF-β and PD-L1 in B cells, which inhibits the anti-tumor effects of T cells." (PMID 40688079, 2025). "Analysis of tumor tissues indicated that, compared to the control group, the concentrations of TNF‐α were significantly elevated in the CB group, AKK group, and CB‐AKK combined group, whereas the concentrations of IL‐6 and IL‐10 were significantly reduced." (PMID 40497373, 2025). "Key among these is interleukin-10 (IL-10), which is secreted predominantly by activated B-cell-like DLBCL (ABC-DLBCL) and fosters an immunosuppressive environment that supports tumor growth, with high IL-10 levels correlating with poor prognosis and treatment resistance." (PMID 40801653, 2025). "Key cytokines—IL-10, TGF-β, and IL-35—are major contributors to this immunosuppressive milieu, each exerting distinct yet overlapping effects that collectively impair anti-tumor immune responses." (PMID 40281554, 2025). "However, in the tumor microenvironment, macrophages are often polarized to the M2 type, which secrete cytokines such as IL-10 and TGF-β that promote tumor cell proliferation, angiogenesis, and immune escape, which are detrimental to tumor control." (PMID 40529813, 2025). "The released IL-10 activated the STAT1/STAT3 signaling pathway to alleviate CAP-induced endoplasmic reticulum stress in tumor cells, finally resulting in attenuation of programmed death of tumor cells after CAP exposure." (PMID 41145470, 2025). "Additionally, the study showed that IL-10 expression preserved mitochondrial structure and increased oxidative phosphorylation in the CAR-T cells, leading to enhanced tumor-killing capacity." (PMID 41584600, 2025). "Moreover, tumor-associated macrophages (TAMs) in EGFR-mutated NSCLC exhibit an immunosuppressive M2 phenotype, secreting factors like IL-10 and VEGF, which promote tumor progression and immune evasion." (PMID 40733125, 2025). "Research has shown that macrophages present viral antigen and IL-10 downregulates MHC-II of macrophages, inhibits the antigen-presenting ability of macrophages, decreases viral clearance, and increases tumor cell infection and tumor cell antigen release." (PMID 40469178, 2025). "According to Vesely and colleagues, tumor cells inhibit the function of effector T cells and promote the accumulation of immunosuppressive cells by secreting factors such as TGF‐β and IL‐10, a strategy that enables tumors to grow and metastasize while escaping immune surveillance." (PMID 41179708, 2025). "Tregs suppress dendritic cell antigen presentation and induce T cell exhaustion within the tumor microenvironment through the secretion of suppressive cytokines, including TGF-β, IL-35, and IL-10, as well as by modulating the expression of inhibitory receptors." (PMID 40236700, 2025).